TUSC7 (tumor suppressor candidate 7)
Synonyms: LINC00902; LOC285194; LSAMP-AS3; NCRNA00295
Gene: Long non-coding RNA gene on chromosome 3 (116,709,235 to 116,723,581, forward strand). Ensembl gene ENSG00000243197.
Diseases named in the same sentence as TUSC7 in open-access papers:
TUSC7 is named in the same sentence as 29 diseases in open-access papers, as found by Europe PMC text mining. Sharing a sentence is not in itself a finding about the gene and the disease. The quoted sentences say what the papers report.
osteosarcoma (14 papers, 2016 to 2025). A usually aggressive malignant bone-forming mesenchymal neoplasm, predominantly affecting adolescents and young adults. "On the other hand, abundance of two types of lncRNAs, MEG3 and TUSC7 were demonstrated to be down-regulated in osteosarcoma patients and significantly associated with survival times." (PMID 28415638, 2017). "Low TUSC7 expression is associated with poor survival (HR=0.313, 95% confidence interval (CI) 0.092–0.867) in osteosarcoma patients." (PMID 27685633, 2016). "Loss of TUSC7 copy number is also associated with a poor prognosis (HR=3.994, 95% CI: 1.147–13.91) in osteosarcoma patients." (PMID 27685633, 2016). "TUSC7 has been characterized as a novel tumor suppressor in multiple cancers, including osteosarcoma, endometrial carcinoma, colorectal cancer, and pancreatic carcinoma." (PMID 40056063, 2025). "TUSC7 inhibited the proliferation, migration of osteosarcoma cells and promoted cellular apoptosis largely through miR-211." (PMID 31652435, 2019). "Spearman correlation analysis indicated that miR-211 was inversely correlated with TUSC7 expression in human osteosarcoma samples." (PMID 31652435, 2019). "TUSC7 inhibited the proliferation, migration of osteosarcoma cells and promoted cellular apoptosis, which is largely mediated by miR-211." (PMID 31652435, 2019). "We then evaluated the correlation between TUSC7 and miR-211 expression in human samples and found that TUSC7 was significantly down-regulated in osteosarcoma tissue." (PMID 31652435, 2019). "Herein, the aim of the study was to investigate the mechanism by which TUSC-7 functions as a potential tumor suppressor in osteosarcoma." (PMID 31652435, 2019). "Frequent deletions in the 3q13.31, including LSAMP and TUSC7, have also been identified in patients with osteosarcomas." (PMID 29736186, 2018). "TUSC7 suppression also increased osteosarcoma growth in a mouse model, and was correlated with poor survival of osteosarcoma patients." (PMID 29441193, 2018). "Two different lncRNAs were down-regulated in osteosarcoma cells, the silence of TUSC7 promoted tumor growth in vivo, and the overexpression of GAS5 inhibited OS cell growth in vitro and in vivo." (PMID 29245999, 2017). "Silence of TUSC7 in MG-63 promoted osteosarcoma growth in subcutaneous inoculation of MG-63+si-TUSC7 produced osteosarcoma xenograft models." (PMID 29245999, 2017). "Recent studies indicated that lncRNA TUSC7 is downregulated in cancers including gastric cancer, osteosarcoma, colorectal cancer (CRC), esophageal squamous cell carcinoma (ESCC), and so on." (PMID 27002617, 2016). "Tumor suppressor candidate 7 (TUSC7) is a potential tumor suppressor that has been shown to inhibit cell proliferation in osteosarcoma." (PMID 27685633, 2016). "Additionally, TUSC7 suppresses the proliferation and migration of osteosarcoma cells through its interaction with miR‐375." (PMID 40056063, 2025). "Notably, TUSC7 has been identified as significantly downregulated in various cancers, demonstrating tumor suppressive effects, including in osteosarcoma, endometrial carcinoma, colorectal cancer, and pancreatic carcinoma." (PMID 40056063, 2025). "MiR-211 was up-regulated in osteosarcoma and negatively correlated with the expression of TUSC7." (PMID 31652435, 2019). "Our result may potentiate the use of TUSC7/miR-211 axis as a novel therapeutic target in osteosarcoma." (PMID 31652435, 2019). "miR-211 and TUSC7 are likely to be promising new therapeutic targets in osteosarcoma." (PMID 31652435, 2019). "LncRNA tumor suppressor candidate 7 (TUSC-7) was shown to be a tumor suppressor in osteosarcoma." (PMID 31652435, 2019). "Depletion of TUSC7 promoted proliferation and inhibited apoptosis in osteosarcoma cells." (PMID 29441193, 2018). "This study reported that silence of TUSC7 promoted osteosarcoma growth both in vitro and in vivo." (PMID 29245999, 2017). "One study reported that long non-coding RNA TUSC7 was down-regulated in osteosarcoma cells." (PMID 29245999, 2017).
osteosarcoma (continued). "Silencing TUSC7 increased osteosarcoma cell proliferation ability and colony formation ability." (PMID 27685633, 2016). "Recent studies have revealed that some lncRNAs such as lncRNA BC040587, lncRNA TUSC7, and lncRNA MALAT1, which are differentially expressed in osteosarcoma, are involved in the progression of osteosarcoma." (PMID 32960485, 2021). "Cong and Jing reported a tumor suppressor, tumor suppressor candidate 7 (TUSC7), which inhibited the proliferation and migration of osteosarcoma cells, promoted cellular apoptosis, and was largely mediated by miR-211." (PMID 33117693, 2020). "However, the regulation mechanism of TUSC-7 in osteosarcoma is unknown." (PMID 31652435, 2019). "The lncRNA TUSC7 (tumor suppressor candidate 7), previously named as LOC285194, was significantly downregulated in osteosarcomas." (PMID 29441193, 2018). "The altered lncRNA expression profile possessed a total of 9 individuals, yet 7 of them (TUG1, 91H, HULC, BANCR, FGFR3-AS1, HOTTIP, and OMRUL) were overexpressed in osteosarcoma tissues/plasma, and 2 (MEG3 and TUSC7) were down-regulated." (PMID 28415638, 2017). "Till now, the prognostic roles of multi-types of lncRNAs have been investigated in osteosarcoma as well, consisting of HULC, HOTTIP, MEG3, TUSC7, TUG1, 91H, and OMRUL, etc." (PMID 28415638, 2017). "In sum, we reported that miR-211 is up-regulated in osteosarcoma and it demonstrates negative correlation with TUSC7 levels." (PMID 31652435, 2019). "Similarly, expression level of TUSC7 was lower in osteosarcoma tissues than non-tumor tissues, and that silencing of TUSC7 expression in osteosarcoma cells resulted in promoted cell viability." (PMID 28415638, 2017).
gastric cancer (12 papers, 2016 to 2023). A primary or metastatic malignant neoplasm involving the stomach. "Studies also continue to indicate that TUSC7 loss plays a role in the poor disease-specific survival (DSS) in patients with gastric cancer and colorectal cancer." (PMID 28938655, 2017). "It has been shown that TUSC7 was downregulated in gastric cancer tissues, and overexpressed TUSC7 reduced the growth of gastric cancer cells in vivo and in vitro by inhibiting the expression of miR-23b." (PMID 38054829, 2023). "Compared with the adjacent normal tissue samples, lncRNA TUSC7 in gastric cancer tissues is significantly lower." (PMID 34375306, 2021). "Effects of miR-23b overexpression in gastric cancer cells were found to include increased cell growth and reversal of TUSC7 overexpression-mediated decrease in cell growth." (PMID 26978351, 2016). "The situations in gastric cancer are sketched by tumor suppressor candidate 7 (TUSC7)/miR-23b, H19/miR-141, and maternally expressed 3 (MEG3)/miR-141." (PMID 26788991, 2016). "TUSC7, downregulated in gastric cancer, was an independent prognostic marker of disease-free survival in patients, and its ectopic expression suppressed cancer cell growth both in in vitro and in vivo models, in part by negatively regulating the expression of miR-23." (PMID 29147648, 2017). "Besides, low expression of TUSC7 are poor prognostic factors for disease free survival (DFS) in human gastric cancer (GC), hepatocellular carcinoma (HCC), CRC, ESCC, as well as NSCLC." (PMID 28938655, 2017). "Moreover, by repressing miR-23b transcription, TUSC7 inhibited cellular proliferation, migration and invasion and promoted cellular apoptosis in gastric cancer and glioma cells." (PMID 28938655, 2017). "The tumor suppressor role of TUSC7 was also demonstrated in gastric cancer." (PMID 29147648, 2017). "It was also shown that TUSC7 is a key regulatory hub in gastric cancer, suggesting that biomarkers or therapeutic interventions may be developed using this lncRNA." (PMID 26978351, 2016). "Therefore, the significant downregulation of TUSC7 in gastric cancer likely allows for the oncogenic characteristics of miR-23b to run unopposed." (PMID 26978351, 2016). "TUSC7 serves as a potential tumor suppressor in some malignancies, including CRC, non-small cell lung cancer, hepatocellular carcinoma and gastric cancer." (PMID 38054829, 2023). "It has been reported that lnc tumor suppressor candidate 7 (TUSC7) was downregulated and acted as a tumor suppressor in many cancers, such as colorectal cancer, glioma and gastric cancer." (PMID 29530057, 2018). "Recently, it has been found that TUSC7 is down-regulated and serves as a potential tumor suppressor gene in several malignancies, including CRC, non-small cell lung cancer, hepatocellular carcinoma and gastric cancer." (PMID 38054829, 2023).
glioma (12 papers, 2017 to 2025). A benign or malignant brain and spinal cord tumor that arises from glial cells (astrocytes, oligodendrocytes, ependymal cells). "Low expression of TUSC7 was associated with poor prognosis in patients with gliomas and could target microRNA (miR)-10a-5p." (PMID 37100464, 2023). "Dual-luciferase reporter gene assays further confirmed that overexpressed TUSC7 can bind to and significantly inhibit miR-10a-5p expression, thereby suppressing human glioma cell proliferation." (PMID 38967893, 2024). "In this study, the expression profiles of lncRNAs were analyzed via bioinformatics approaches, and lncRNA tumor suppressor candidate 7 (TUSC7), which was down-regulated in gliomas, was identified from RNA-seq." (PMID 37100464, 2023). "In this study, although it has been proven that TUSC7 acts as a tumor suppressor in gliomas and has the potential to be a biomarker, in vivo and in vitro experiments are still needed for further validation, thus providing bases for clinical transformation." (PMID 37100464, 2023). "Bioinformatics analysis indicated that TUSC7 specifically binds to miR-23b, which was up-regulated in glioma and negatively correlates with the expression of TUSC7." (PMID 30583549, 2018). "The expression of TUSC7 is down-regulated in glioma tissue and negatively correlates with the overall survival of the patients and expression of miR-23b." (PMID 30583549, 2018). "The expression level of TUSC7 negatively correlated with the histological grades of gliomas and was a prognostic biomarker in glioma patients." (PMID 30217088, 2018). "Our previous study showed that another lncRNA, TUSC7 (tumor suppressor candidate 7), was targeted and inhibited reciprocally by miR-23b, and acted as a tumor-suppressor gene in glioma cells." (PMID 28146436, 2017). "The expression levels of BDNF, p-TrkB and ERK1/2 markedly decline after overexpression of TUSC7, whereas they are evidently raised after silencing TUSC7, suggesting that TUSC7 can suppress the proliferation and migration of glioma cells through inhibiting the BDNF/TrkB/ERK pathway." (PMID 37100464, 2023). "Furthermore, the luciferase reporter gene assay was used to validate the binding of TUSC7 to miR-10a-5p in glioma cells." (PMID 37100464, 2023). "It was speculated that TUSC7 may exert important effects in the occurrence and progression of gliomas and possibly functions as a tumor suppressor gene." (PMID 37100464, 2023). "Thus, TUSC7 was hypothesized to repress the proliferation and migration of glioma cells by specifically binding to intracellular miR-10a-5p." (PMID 37100464, 2023). "According to Western blotting results, TUSC7 overexpression group had significantly lower expressions of MMP2, MMP3 and MMP9 than NC group, whereas they were obviously elevated after silencing TUSC7, suggesting that TUSC7 could inhibit the migration of glioma cells by degrading MMP2, MMP3 and MMP9." (PMID 37100464, 2023). "Methods and results: In this study, bioinformatics analysis indicated that TUSC7 could specifically bind to microRNA (miR)-10a-5p, and according to quantitative polymerase chain reaction (q-PCR), miR-10a-5p was up-regulated in human glioma cells and negatively correlated with TUSC7 expression." (PMID 37100464, 2023). "Tumor suppressor candidate 7 (TUSC7) expression was found down regulated in HCC, NSCLC, pancreatic carcinoma, colorectal cancer, glioma and other tumor types." (PMID 31003545, 2019). "Tumor suppressor candidate 7 (TUSC7), another tumor suppressor lncRNA, was downregulated in 39 glioma samples compared to 17 adjacent healthy brain tissues." (PMID 30217088, 2018). "Bioinformatic analysis revealed increased miR-10a-5p levels in human glioma cells, showing a negative correlation with TUSC7, a tumor suppressor candidate." (PMID 41551164, 2025). "Quantitative polymerase chain reaction (qPCR) revealed significant upregulation of miR-10a-5p in glioma cells, which showed a negative correlation with TUSC7 expression." (PMID 38967893, 2024).
colorectal cancer (10 papers, 2013 to 2025). A primary or metastatic malignant neoplasm that affects the colon or rectum. "In addition, serum TUSC7 level displayed a high diagnostic value for patients with colorectal cancer." (PMID 28938655, 2017). "TUSC7 has been proven to be down-regulated in multiple tumors, such as liver cancer, colorectal cancer, and endometrial cancer." (PMID 37100464, 2023). "Another study also showed that the overexpression of TUSC7 can significantly inhibit the proliferation, migration, invasion, and EMT of colorectal cancer cell." (PMID 35264071, 2022). "LSAMP-AS1, also called LOC285194 or Tumor Suppressor Candidate 7(TUSC7), was previously defined as a tumor suppressor in esophageal squamous cell carcinoma (ESCC) and colorectal cancer." (PMID 31367490, 2019). "For the last 5 years, many reports have revealed that decreased TUSC7 expression is correlated with unfavorable overall survival (OS) in various tumors, including non-small-cell lung cancer (NSCLC), colorectal cancer (CRC), esophageal squamous cell carcinoma (ESCC), osteosarcoma (OSA) and so on." (PMID 28938655, 2017).
esophageal squamous cell carcinoma (7 papers, 2016 to 2024). Esophageal squamous cell carcinoma (ESCC) is a type of esophageal carcinoma (EC) that can affect any part of the esophagus, but is usually located in the upper or middle third. "This study aims to clarify the underlying mechanism for the tumor suppressive function of lnc TUSC7 in chemotherapy resistance of esophageal squamous cell carcinoma (ESCC)." (PMID 29530057, 2018).
glioblastoma (5 papers, 2020 to 2023). The most malignant astrocytic tumor (WHO grade IV). "TUSC7 inhibits the chemoresistance of esophageal cancer and glioblastoma cells by sponging miR-224-5p and miR-10a-5p, respectively." (PMID 37190145, 2023). "Co-expression analyses confirmed the following interrelations: MALAT1–TYMS, MALAT1–MRP5, H19–ZEB1, CASC2–VIM, CASC2–N-CAD; they additionally suggest the possibility of MALAT1–BCRP, MALAT1–mTOR and TUSC7–PTEN interconnections in glioblastoma." (PMID 33245508, 2022). "Expression of TUSC7 has been decreased in TMZ-resistant glioblastoma cells and tissues." (PMID 34178658, 2021). "Consequently, curcumin may suppress the chemoresistance of esophageal cancer and glioblastoma cells by modulating the TUSC7–miR-224-5p/miR-10a-5p axis." (PMID 37190145, 2023). "Curcumin upregulates tumor-suppressor candidate 7 (TUSC7), which exhibits low levels in esophageal cancer and glioblastoma tissues and cells, providing the inhibition of chemoresistance." (PMID 37190145, 2023). "The following lncRNAs engaged in glioblastoma therapy resistance were selected: MALAT1, CASC2, H19, TUSC7, XIST, RP11-838N2.4, DLX6-AS1, GLIDR, MIR210HG, SOX2-OT." (PMID 33245508, 2022). "Notably, expressions of oncogenic lncRNAs lnc-TALC, LncSBF2-AS1, MALAT1, TP73-AS1, and H19 as well as expression of tumor suppressor lncRNAs AC003092.1, TUSC7, and RP11-838N2.4 have been shown to alter this phenotype in glioblastoma cells." (PMID 33634032, 2020).
hepatocellular carcinoma (5 papers, 2016 to 2023). A malignant tumor that arises from hepatocytes. "For example, TUSC7 was shown to inhibit EMT by targeting miR-10a in hepatocellular carcinoma cells." (PMID 31652435, 2019). "Additionally, TUSC7 acts as a molecular sponge of miR-10a and suppresses EMT through decrease the expression of Eph tyrosine kinase receptor A4 in human hepatocellular carcinoma." (PMID 28938655, 2017).
colon cancer (4 papers, 2016 to 2023). "For instance, the lncRNA TUSC7 can inhibit epithelial-mesenchymal transition (EMT) in colon cancer cells, thus suppressing invasion and metastasis." (PMID 36960218, 2023). "Moreover, the authors determined the expression of TUSC7 in colon cancer tissue by microarrays and showed that TUSC7 was down-regulated in tumor specimens compared with normal specimens." (PMID 27148353, 2016).
pancreatic carcinoma (4 papers, 2019 to 2025). "Moreover, TUSC7 attenuates pancreatic cancer progression by regulating miR‐371a‐5p." (PMID 40056063, 2025).
lung carcinoma (3 papers, 2016 to 2021). "In this study, we identified the inhibitive roles of TUSC7 in lung cancer progression, and after acquiring the Erlotinib resistant cells, gene panel was used for massive assessing of the dysregulated non-coding RNAs." (PMID 34656164, 2021). "Moreover, TUSC7 upregulation inhibited lung cancer cell proliferation in vitro." (PMID 27685633, 2016). "In their studies, they found that the expression levels of TUSC7 were lower in NSCLC tissues and lung cancer cells compared with that in normal tissues and cells." (PMID 27685633, 2016).
breast carcinoma (2 papers, 2019 to 2021). "There are three lncRNAs are confirmed to be associated with breast cancer in the Lnc2cancer database, which are PTENP1, SNHG16 and TUSC7, respectively." (PMID 33980147, 2021). "We showed that the lncRNA TUSC7 acted as a tumor suppressor gene, which was negatively regulated by miR-211, an miRNA that was demonstrated to play a critical roles in tumorigenesis of breast cancer." (PMID 31652435, 2019).
esophageal cancer (2 papers, 2021 to 2023). A primary or metastatic malignant neoplasm involving the esophagus. "Moreover, overexpression of TUSC7 inhibits tumor growth and chemoresistance in the esophageal cancer xenograft model." (PMID 37190145, 2023). "Moreover, esophageal cancer patients with lower lncRNA TUSC7 expression had short OS." (PMID 34881242, 2021).
lymph node metastasis (2 papers, 2016 to 2017). "In human pancreatic ductal adenocarcinoma (PDAC) and CRC, by analyzing the association of TUSC7 expression with clinicopathologic features, it was found that low TUSC7 expression was closely correlated with lymph node metastasis, liver metastasis, and more distant metastases." (PMID 27002617, 2016).
acute myeloid leukemia (1 paper, 2018). Acute myeloid leukemia (AML) is a group of neoplasms arising from precursor cells committed to the myeloid cell-line differentiation. "The authors also showed that, although the patient with acute myeloid leukemia had a 250-kb deletion in 3q13.31, which included the TUSC7 gene but not LSAMP, the expression of both genes was increased by an unknown mechanism." (PMID 29736186, 2018).